CD86 (CD86 molecule)
Diseases named in the same sentence as CD86 in open-access papers (continued):
Sharing a sentence is not in itself a finding about the gene and the disease.
cancer (continued). "As predicted, the administration of P21 to only DCs or cancer cells slightly enhanced DC maturation (CD11C+CD40+, CD80+, or CD86+) compared with the untreated group." (PMID 38994018, 2024). "Low CD86 has been reported in inadequately matured DCs that induce T-cell tolerance, while recognition of CRT on cancer cells by CD91 on macrophages and DC promotes phagocytosis of apoptotic cells and priming of T-helper (Th) lymphocytes." (PMID 37779162, 2023). "Our analysis revealed a positive association between the expression of P2RY6 and immunosuppressive genes such as CD86, CD80, IL2RA, TGFB1, and LGALS9 in pan-cancer." (PMID 37880703, 2023). "The levels of cytokines such as IL1a, IFNB1, CD80, CD86, and CXCL10, which are important for inducing an immune response by macrophages within cancer tissue, were upregulated in PBMCs in a RIG-I-dependent manner." (PMID 37543704, 2023). "The immunological checkpoints selected for the analysis, such as PD-1/PD-L1, CTLA-4/CD86, and CD200R/CD200, play a significant role in regulating the immune response in many diseases, including cancer, and influencing the tumor microenvironment." (PMID 37835480, 2023). "In step 3 of the cancer-immunity cycle, antigen recognition through T cell receptors and the interaction of CD28 on T cells with CD80/CD86 on DCs are necessary for full T cell activation." (PMID 36980950, 2023). "CD80 and CD86 are ligands for CTLA4 and are expressed as markers of M2-type macrophages in various cancers." (PMID 37838657, 2023). "In vitro, PDT with the particles induced cancer cell death, and incubation of PDT-treated cancer cells with BMDC induced upregulation of maturation markers CD80 and CD86." (PMID 36839652, 2023). "CD86 was shown to be a poor prognostic factor in LGG, SKCM, and UVM, similar to our findings in the pan‐cancer analysis." (PMID 35702880, 2023). "Previous studies showed that application of NTP to cancer cells stimulated APC maturation, as evidenced by increased surface expression of the co-stimulatory molecule CD86." (PMID 36672628, 2023). "Subsequently, the correlation between key pan-carcinoma molecules (including CTLA4, PDCD1LG2, IDO1, and HAVCR2) and CD86 was calculated." (PMID 37064861, 2023). "In the present study, SRSF9 expression had been shown to positively correlate with most of the 47 immune checkpoint genes in most cancers, such as CD276, CD86, CTLA-4, and CD40." (PMID 35069733, 2022). "As previously reported, in the cancer-immunity cycle, CD28: (CD80, CD86), CD40, CD27, HVEM, GITR: GITRL, ICOS, and TLR-2 are stimulatory factors, while TIM-3, PD-L1: PD-1, PD-L1: (CD80, CD86), CTLA-4: (CD80, CD86), BTLA, and LAG-3 are inhibitory factors." (PMID 35419462, 2022). "This phenotype of metastatic LN T cells is preceded by the suppression of LN-resident DCs, which are less mature and express decreased levels of the activation markers CD40, CD86 and CD83 than healthy and cancer-free LN DCs." (PMID 36139665, 2022). "Data showed that the many immune checkpoints positively correlate with CD93 expression in many cancers, particularly NRP1, LAIR1, VSIR, and CD86." (PMID 36389798, 2022). "Cancer cells can express regulatory ligands such as PD-L1, CD80/CD86, or Galectin-9 to provide a negative regulatory signal to T lymphocytes expressing their respective receptors PD-1, CTLA-4, and TIM-3, resulting in T cell exhaustion." (PMID 35159351, 2022). "The present analysis found elevated expression of CD47 not only positively correlated with PD1, PD-L1, CTLA4, but also with multiple other immune checkpoints such as IDO1, CD40, CD160, CD86, CD44 across various cancer types." (PMID 35697717, 2022).
cancer (continued). "In this bidirectional way, the interplay of CD86 with CD28 and CTLA‐4 are of great importance for immune responses against autoimmunity and cancers." (PMID 33954112, 2021). "The B. sennaarensisare toxins regulate the expression of MHC-II, CD80, and CD-86, as well as interferon- γ (IFN-γ) and interleukin-17 (IL-17), mediators that are involved in various chronic pathologies and cancer as demonstrated after in vivo tests." (PMID 34795699, 2021). "Methylation of CpGs annotated to the promoters of LAG3, CTLA4, CD86, CD80, and HAVCR2 also decreases with age pan-cancer." (PMID 34433020, 2021). "Antibody-based blockade of CTLA4 binding to CD80/CD86 is reported to promote CD80/CD86 interactions with the immune co-stimulatory signal, CD28, and re-activation of T cell activity to kill cancer cells." (PMID 33406733, 2021). "Markers for T and B cell activation (CD69, CD25, 41BB and CD86) and T-cell differentiation (CD45RA-CCR7- effector memory T cells) were elevated in TILs of advanced stage cancers." (PMID 34135436, 2021). "Regarding gene expression, cancer immune evasion-related genes were found up-regulated in the negative BL samples, such as CD274 (alias PD-L1), IDO1, LAG-3, CTLA4, and CD80 and CD86 genes, required for the activation of the inhibitory activity of CTLA4." (PMID 34680332, 2021). "Irradiating a co-culture of immature dendritic cells (DCs) and cancer cells exposed to light-activated ZHER2:2395-IR700 enhanced DC maturation, as indicated by augmented expression of CD86 and HLA-DR." (PMID 33082328, 2020). "The basal expression of the CD80, CD86 and HLA-DR molecules in the three APC populations was largely comparable between the healthy subjects and the cancer patients, before and after chemotherapy." (PMID 31973714, 2020). "Recent studies have suggested that immune checkpoints play an important role in the immune escape of cancer, so we further analysed the relationship between the 4 subtypes and 8 immune checkpoint genes (PDCD1, CD274, PDCD1LG2, CTLA4, CD86, CD80 and CD267)." (PMID 31995855, 2020). "Particularly, SPARC and SPP1 expression were positively correlated to DC-related markers CD86, NRP1, and inhibitory checkpoint markers including LAIR1, HAVCR2, and PDCDLG2 in most cancer types." (PMID 33240930, 2020). "The total number of activated CD103+ CD86+ and of CD103+ CD80+ cell subsets rose 10% and 12% by FACS, respectively, in the immune cells co-cultured with Poly(I:C)/INFα-treated-H460 cancer cells versus untreated H460 cells." (PMID 32093313, 2020). "KIR2DL2/L3/S2+ CD8+ T lymphocytes exhibited over-expression of genes that are not usually expressed in CD8+ T cells, i.e., EGFR, ITGB1, MAP2K1, and CD86, indicating that these cells are reprogrammed to the AKT/PI3K cancer pathway." (PMID 33076479, 2020). "Immunosuppressive activity of certain cancer cells is gained by expression of CD80 and CD86.102,103 CTLA-4 and CD28 (co-receptor of TCR) recognize the same ligands." (PMID 32555170, 2020). "The expression of CD80, CD86 and HLA-DR molecules was evaluated in CD14−CD123+ plasmacytoid dendritic cells (pDCs) from cancer patients, before and after chemotherapy, upon ex vivo treatment with the adjuvants." (PMID 31973714, 2020). "For the myeloid-derived cancer cell lines, we identified specific surface markers (e.g., ITGAM, ITGAX, CD68, CD86) usually present on monocytes, neutrophils, and macrophages, positively contributing to the BAY-155, EPZ-5676, and Brequinar group." (PMID 31253180, 2019). "We therefore evaluated the expression of maturation markers, namely MHC-II, CD80, and CD86, upon exposure to PDT-killed cancer cells." (PMID 31508370, 2019). "We studied the expression of CD80, CD86 and MHC-II on the surface of B lymphocytes from cancer patients, compared to cells from healthy donors." (PMID 29975708, 2018).
cancer (continued). "Another known mechanism of immune evasion by cancer cells is to increase their expression of checkpoint ligands, such as PD-L1, CD80, and CD86 and promote T cell tolerance." (PMID 30740111, 2018). "Co-incubation of heat-stressed apoptotic cancer cells with immature DCs resulted in the upregulation of DC maturation markers (CD40, CD80, and CD86) and higher IL-12 levels." (PMID 26834740, 2015). "Our data revealed CD86+/F4/80+ (M1) and CD206+/F4/80+ (M2) cells in peritoneal washes and ascitic fluids 3 and 7 days after inoculation with cancer cells." (PMID 24992906, 2014). "For example, intra-tumoral DCs obtained from cancer patients or cancer-bearing experimental animals display lower expression of MHC class I and II as well as CD80 and CD86 molecules." (PMID 24782988, 2014). "For example, administration of B7-1 (CD80) and B7-2 (CD86), proteins that provide the crucial second signal required for T-cell activation, has been shown to increase CTL activity in cancer and HIV, respectively." (PMID 24204366, 2013). "Our data confirm that in cancer patients, DCs display an 'immature' phenotype with lower levels of accessory signals for T cell activation such as CD80 and CD86 than those expressed on DCs from normal healthy controls." (PMID 20565840, 2010). "To further characterize DCs in cancer patients, we next determined their expressions of the surface markers HLA-DR, CD80, and CD86 by flow cytometry." (PMID 20565840, 2010). "Mature MDDC from healthy donors and cancer patients up-regulated the expression of CD83, CD86, frequencies of IL-12+ and COX-2+ cells, and secretion of IL-8; and down-regulated CD209 expression relative to their immature counterparts." (PMID 17477875, 2007). "In fact, LPS-induced upregulation of CD80, CD86 and CD83, and the expression of IL-10 were similar in cancer patients and healthy controls." (PMID 14562018, 2003). "Furthermore, co-culturing immature dendritic cells with dying cancer cells targeted by EGFR and TF NIR-PIT agents mediated enhanced dendritic cell maturation, as indicated by increased expression of CD80, CD86, CD40, and HLADR." (PMID 41362788, 2025). "The expressions of MHC molecule H-2Kb and co-stimulator factors (CD80 and CD86) on the surface of macrophages were not affected by the co-culture of lamin-deficient cancer cells, suggesting that lamin knockdown in cancer cell might not influence macrophage activation." (PMID 40708945, 2025). "Conversely, the expression levels of CD47 and CD86 proteins on cancer cells were not affected by lamin knockdown." (PMID 40708945, 2025). "These ligands, such as programmed cell death ligand 1, CD86, GAL-9, and VISTA, may partly explain the reduced T-cell-mediated activation and killing of PRAME-overexpressing cancer cells." (PMID 40933628, 2025). "Interestingly, CM from the Cat D KO (KO-CM) Caki cancer cells suppressed the polarization of THP-1 macrophages into CD204+ TAMs and promoted CD86+ TAMs compared with CM from the control cells (WT-CM)." (PMID 38297161, 2024). "Indeed, the co-culture of DCs with HN-1-pretreated cancer cells significantly promoted CD83 and CD86 expression." (PMID 38970078, 2024). "Thus, cancer cell fragments generated by carbon ion irradiation induce cancer-specific CD8+ T cells through the cross-presentation of CD80 and CD86 on DCs." (PMID 38474078, 2024). "CD80 and CD86, while not as well characterized clinically, demonstrate similar immunosuppressive changes when expressed on cancer cells." (PMID 38542481, 2024). "In cancer, CTLA4 is harnessed by cancer cells to hinder the antitumor immune response through manipulation of the expression of CTLA4 ligands (CD80 and CD86) on APCs within the tumor microenvironment, enabling CTLA4 on regulatory T cells (Tregs) to suppress cytotoxic T cell activity." (PMID 39409893, 2024).
cancer (continued). "In addition, the expression of CD80 and CD86 was further increased when the macrophages were stimulated with LPS and IFN-γ before coculture with HER2-positive cancer cells in both the GFP-M and CAR-M groups." (PMID 36978075, 2023). "We observed that the proportion of MHC-II+ cells and CD86+ cells in DCs was significantly reduced in cancer-bearing mice compared to non-cancer-bearing mice." (PMID 37553633, 2023). "Moreover, Hyp PDT induced phagocytosis of cancer cells by DCs and induced upregulation of maturation markers CD80, CD86 and CD40 to a larger extent than DCs co-cultured with F/T treated cancer cells." (PMID 36839652, 2023). "The proportion of CD80+ cells and CD86+ cells in CD11b−F4/80+ cells were significantly lower in cancer-bearing mice than in non-cancer-bearing mice." (PMID 37553633, 2023). "Interestingly, TAMs (CCL2, CD86, and IL10), M1 [INOS(NOS2), IRF5, and COX2(PTGS2)] were significantly correlated with SHC1 expression in the three cancers." (PMID 35601500, 2022). "In addition, we explored the immunological effects of FOSCAN-PDT-treated cancer cells by analyzing the expression of the co-stimulatory molecules CD40, CD86, and major histocompatibility complex (MHC)-II on the surface of DCs after 24 h of co-culture." (PMID 35681703, 2022). "Cancer cells also present the HLA class II antigen in the absence of the CD80/CD86 universe-stimulating molecules, this frequent representation of cancer cell antigens drives T-cell anergy thus, imparting cancer tolerance." (PMID 35517798, 2022). "In addition, a correlation analysis between NET score and 45 immune checkpoint genes (ICGs) revealed that CD48, CD86, and LAIR1 were the most significant NET-related checkpoint genes in all cancer types." (PMID 35432310, 2022). "In various types of cancer, findings between NNMT and immunostimulator gene expression showed a high connection (p < 0.05), including TNFSF13B, TNFRSF8, TNFSF14, IL6, IL2RA, CD80, CD27, and CD86." (PMID 36386816, 2022). "Stimulation with HKTB significantly induced expressions of CD86+ macrophages in both cancer and healthy groups without a significant change in the expression of CD206+ macrophages, indicating a promotion towards the proinflammatory phenotype." (PMID 35477732, 2022). "In sentinel lymph nodes, mature DCs (identified as CD86+MHC II+) increased robustly in the HA-man@Fe3O4 plus HA-man@Fe3O4@pep group, while free peptides failed to arouse mature DCs, suggesting the necessity of adjuvant and carrier in cancer vaccination." (PMID 36291890, 2022). "Moreover, the link between CTLA4, PDCD1, CD86, CD274, and ISCA1 in various cancer types was measured." (PMID 36072584, 2022). "Ultimately, HDIs may regulate cancer cell immunogenicity by upregulating molecules participating in T-cell and natural killer cell activation, such as MHC class I and II, CD80/CD86, and MHC class I chain-related molecules (MICA/MICB)." (PMID 34769131, 2021). "OSCAR expression was positively correlated with infiltrating levels of monocytes in 20/20 types of cancer, especially BLCA (CD86, r=0.718; CD115, r=0.740), CESC (CD86, r=0.756; CD115, r=0.700), THCA (CD86, r=0.836; CD115, r=0.732), and UCEC (CD86, r=0.775; CD115, r=0.727)." (PMID 34093786, 2021). "Discovery of the B7 family immune checkpoints such as CTLA-4 (CD152), PD-1 (CD279), as well as their ligands B7-1 (CD80), B7-2 (CD86), B7-H1 (PD-L1, CD274), and B7-DC (PD-L2, CD273), has opened new possibilities for cancer immunotherapy using monoclonal antibodies (mAb)." (PMID 33419027, 2021). "To evaluate how CPEB3 in CRC cells may inhibit M2-like TAM polarization, we first assessed the expression of CPEB3, CD86 and CD163 in 82 pairs of CRC tissues and adjacent non-cancer tissues using qRT-PCR." (PMID 32653013, 2020).
cancer (continued). "Phagocytosis was proven, using 5-chloromethylfluorescein diacetate (CMFDA), to pre-label cancer cells and, more importantly, DC maturation was documented by the increased expression of co-stimulatory molecules CD40, CD80 and CD86." (PMID 32120810, 2020). "On the contrary, CD86 expression was high in healthy subjects and showed limited variation in cancer patients, without reaching a statistical significance." (PMID 31973714, 2020). "CD86 (B7-2), one of the checkpoint proteins in antigen-presenting cells (APCs), interacts with CD28 and cytotoxic T lymphocyte antigen‐4 (CTLA‐4) receptors on T cells, thereby limiting T-cell activation and inducing immunoescape of cancers." (PMID 33425732, 2020). "Moreover, CD80 (B7-1), B7-2 (CD86)/CTLA-4, and B7-H1 (PD-L1)/PD-1 have been identified as promising targets and their inhibitors have achieved great success in cancer immunotherapy." (PMID 30609841, 2019). "mDCs manufactured using GM-CSF and IL-4 primed with OK-432 for clinical use expressed the HLA−ABC+DR+CD40+CD80+CD86+CD197+ phenotype, harboring bioactive functions that could be useful in providing personalized vaccines for cancer immunotherapy." (PMID 31546936, 2019). "These dying cancer cells are efficiently phagocytosed by BMDCs, inducing their maturation and activation in a manner that depends on the ratio of the two cell types, as evidenced by increased surface expression of CD40 and CD86." (PMID 31842994, 2019). "MCA205 cancers treated with (R)-crizotinib, alone or together with CDDP, exhibited a significant increase (p < 0.001, ANOVA test) in the local presence of activated dendritic cells (DC) expressing CD11c and CD86, CTL." (PMID 30940805, 2019). "Considering the different affinity of CD86 and CD80 for CD28 and CTLA-4, respectively, and the constitutive expression of CTLA-4 in Treg cells, cancer cells could induce antigen tolerance towards themselves by modulating Treg cell functions." (PMID 30123257, 2018). "The products of several genes from our potential cell surface list are suspected of playing key roles in more general cancer-related activities such as immunosuppression/evasion (CD14 and CD86), cell migration (ICAM, CDH11) and proliferation (TGFB1, PMEPA1, PDGFRL, SLC19A3)." (PMID 27363029, 2016). "Interestingly, HHP-treated cancer cells were rapidly phagocytosed by DCs and induced the upregulation of CD83, CD86, and HLA-DR, and the release of pro-inflammatory cytokines." (PMID 26834740, 2015). "In addition, we also found that the presence of HDAC7 led to the upregulation of genes related to immune processes (IL16, FCGR2A, IRAK2, CD86 and CD40, among others) and cancer (RASSF4, RAB31, NEDD9 and RASSF2, among others)." (PMID 25675295, 2015). "To study this hypothesis, we used FACS analysis to quantify the expression of the three target receptors of CTLA4-FasL, namely CD80 (B7.1), CD86 (B7.2) and CD95 (Fas), on the different human cancer cell lines." (PMID 25227919, 2014). "Interestingly, multiple genes encoding cell surface immune checkpoint receptors and their ligands were transcriptionally regulated by IRF4, including PD-L1 (CD274), PD1 (CD279), CTLA4 (CD152), B7-2 (CD86), LAG3 (CD223), and PD-L2 (CD273), in these virus-infected cancer cells." (PMID 40733503, 2025). "However, we discovered that CD48, CD86, and HAVCR2 were common factors in both cohorts, indicating a potential synergistic effect by targeting both ferroptosis pathways and immune checkpoints in cancer therapy." (PMID 40744688, 2025). "This targeting mechanism of ExoDS may be attributed to a variety of membrane receptors like integrin α and β chains (αMβ2), ICAM-1, MFG-E8, TNF, FasL, CD86, CD80, CD40, CD83, MHC-I, MHC-II, NKG2D, IL-15Rα, CD21, CD11c, and CCR7, which help mDC-derived exosomes identify cancer cells." (PMID 38903193, 2024).